UBE2S (ubiquitin conjugating enzyme E2 S)
Diseases named in the same sentence as UBE2S in open-access papers (continued):
Sharing a sentence is not in itself a finding about the gene and the disease.
breast carcinoma (continued). "Both qRT-PCR and western blot confirmed increased UBE2S and UBE2C, as well as decreased Numb expression, in breast cancer cell lines compared to MCF10A." (PMID 36860312, 2023). "We found that higher levels of UBE2S and UBE2C and lower expression of Numb were correlated with shorter overall survival (OS) and relapse-free survival (RFS) in breast cancer patients." (PMID 36860312, 2023). "Taken together, UBE2S and UBE2C were worse prognosis predictors in breast cancer patients as well as in ER+ patients, while Numb showed the opposite prognostic effect." (PMID 36860312, 2023). "Among the top 10 genes selected by dwgLASSO, UBE2S, SALL2, XBP1 and KIAA0922 have been previously reported to be relevant in breast cancer biomarker discovery study." (PMID 28187708, 2017). "Notably, the co-expression of UBE2S/UBE2C and Numb was considered as a promising biomarker for breast cancer." (PMID 38312603, 2024). "However, the prognostic effects as well as the collective regulatory mechanisms of both UBE2S and UBE2C in breast cancer remain to be elucidated." (PMID 36860312, 2023). "To explore the expression and potential clinical significance of UBE2S, UBE2C, and Numb in breast cancer, first we analyzed the Oncomine microarray datasets to determine the mRNA levels of UBE2S, UBE2C, and Numb in a variety of malignant tumor types, including breast cancer." (PMID 36860312, 2023). "More specifically, the comparison of UBE2S, UBE2C, and Numb mRNA expression across nine independent analyses demonstrated that UBE2S and UBE2C were markedly elevated and Numb was significantly reduced in breast cancer." (PMID 36860312, 2023). "Apart from ER+ and ER− breast cancers, we also compared the expression of UBE2S, UBE2C, and Numb in PR positive (PR+) and PR negative (PR−) breast cancers as well as in HER2 positive (HER2+) and HER2 negative (HER2−) breast cancers." (PMID 36860312, 2023). "We found that breast cancer tissues with medium or high protein staining of UBE2S and UBE2C had negative or weak staining of Numb protein (Cases 1–3>), whereas the lower protein levels of UBE2S and UBE2C displayed strong staining of Numb protein (Case 4)." (PMID 36860312, 2023). "Oncomine, Cancer Cell Line Encyclopedia (CCLE), the Human Protein Atlas (HPA) database, qRT-PCR, and Western blot analyses were utilized to analyze UBE2S/UBE2C and Numb expression in various cancer types and their respective normal controls, breast cancer tissues, and breast cancer cell lines." (PMID 36860312, 2023). "Besides, HECTD3, PSMB10, UBD, UBE2C, and UBE2S involved in the ubiquitin proteasome pathway, as well as CCL2, CCR1, CXCL10, CXCL11, and IL2RG implicated in the cytokine–cytokine receptor interaction pathway, might be used for evaluating the efficacy of neoadjuvant chemotherapy in breast cancer." (PMID 29685151, 2018). "As important members of the E2 family, it was reported that UBE2S and UBE2C were highly expressed in cancerous tissues compared with surrounding normal tissues, and aberrant expression of the genes was reported to be involved in tumorigenesis and tumor progression, including breast cancer." (PMID 36860312, 2023). "Consistently, we found out that the copy numbers of UBE2S and UBE2C were significantly upregulated in breast cancer cell lines and rank relatively high among various cancer cell types through CCLE analysis, while the Numb copy number was relatively low in breast cancer cell lines." (PMID 36860312, 2023). "The expression of UBE2S and UBE2C was generally higher and Numb expression was lower in various cancer types than their respective normal controls, especially in breast cancer, although no obvious differential expression of Numb was shown in certain cancers." (PMID 36860312, 2023). "However, no statistical significance of UBE2S, UBE2C, or Numb expression was observed between HER2+ and HER2− breast cancer." (PMID 36860312, 2023).
breast carcinoma (continued). "However, the interaction between UBE2S/UBE2C and Numb and their roles in the clinical outcome of breast cancer (BC) are not widely elucidated." (PMID 36860312, 2023).
glioma (12 papers, 2021 to 2025). A benign or malignant brain and spinal cord tumor that arises from glial cells (astrocytes, oligodendrocytes, ependymal cells). "Additional studies show that UBE2S expression is strongly associated with malignancy and resistance to chemoradiation in glioma, thus, an important biomarker of a poor prognosis." (PMID 38115063, 2023). "The UBE2S gene is associated with a poor prognosis for cancers such as breast and gliomas, liver, and other malignant tumors." (PMID 36534449, 2022). "The incidence of malignant factor, EGFR amplification and PTEN mutation, was significantly higher in glioma samples with higher expression levels of UBE2S compared with those with low expression levels." (PMID 34123793, 2021). "The results showed that high UBE2S expression was associated with a higher grade of glioma and PTEN mutations." (PMID 34123793, 2021). "The underlying mechanism provides a basis for UBE2S as a new molecular target for prevention and treatment of glioma." (PMID 34123793, 2021). "Further analysis on the oncogenic features of UBE2S showed that the genomic or transcriptional alterations associated with the origin or progression of glioma correlated with degrees of UBE2S expression level." (PMID 34123793, 2021). "The expression of UBE2S had a strong connection with the malignancy of glioma and its resistance to chemoradiotherapy." (PMID 41427004, 2025). "The study revealed a significant increase in ETO-induced cell death upon downregulation of UBE2S expression, indicating that UBE2S downregulation heightened the sensitivity of gliomas to ETO in vivo." (PMID 38312603, 2024). "This study presents a clinical and molecular characterization of UBE2S of gliomas, demonstrating its potential as a biomarker of resistance to radiotherapy and poor prognosis." (PMID 38312603, 2024). "Another study has demonstrated that UBE2S was linked to NHEJ-regulated DNA damage repair, which promotes drug resistance in glioma cells." (PMID 38312603, 2024). "For example, UBE2S is used as a new marker to predict the efficacy of radiotherapy and chemotherapy in human glioma." (PMID 38115063, 2023). "In the Sun dataset of glioma (GEO ID: GSE4290), expression of the genes UBE2S and UBE2C, which encode ubiquitin conjugases important for cell-cycle progression, distinguished GBM from AS and ODG." (PMID 35896929, 2023). "Consistent with our data, UBE2S was also overexpressed and predicted poor prognosis in glioma and endometrial cancer 48,49." (PMID 35637955, 2022). "This study shows the potential significance of UBE2S expression in diagnosis and prognosis of glioma and further explored the function of this protein in glioma." (PMID 34123793, 2021). "Abnormal expression of UBE2S in glioma prompted us to explore the clinical relevance of PI3K/Akt/UBE2S oncogenic synergy." (PMID 34123793, 2021). "This study demonstrates that UBE2S expression strongly correlates with glioma malignancy and resistance to chemo-radiotherapy." (PMID 34123793, 2021). "The aim of this study was to explore expression levels of UBE2S in glioma, and to explore the relationship between UBE2S expression and prognosis of glioma, and chemo-radiotherapy resistance." (PMID 34123793, 2021). "Similar findings were obtained with the CGGA cohort which showed that UBE2S expression was highly correlated with the malignancy of glioma." (PMID 34123793, 2021). "UBE2S is therefore a potential novel biomarker and therapeutic target for the treatment of human glioma." (PMID 34123793, 2021). "In summary, these findings show that UBE2S is highly expressed in grades III-IV glioma and the high expression level of UBE2S is correlated with glioma malignancy and chemo-radiotherapy resistance." (PMID 34123793, 2021). "MK-2206 pre-treated glioma cells, which exhibited low UBE2S expression levels, were more sensitive to IR." (PMID 34123793, 2021).
glioma (continued). "Glioma patients were divided into IDH1 mutation group and IDH1 wild-type group and the association between UBE2S expression level and the IDH1 status was determined." (PMID 34123793, 2021). "Similar findings were observed in the TCGA cohort whereby UBE2S expression was significantly correlated with the key molecular characteristics of glioma." (PMID 34123793, 2021). "Kaplan Meier survival curve was used to determine the prognostic value of UBE2S expression in the overall survival (OS) of glioma." (PMID 34123793, 2021). "Recent study reported that UBE2S expression positively correlated with malignancy and resistance to chemo-radiotherapy in glioma." (PMID 34535173, 2021). "In the TCGA cohort, UBE2S expression increased with increasing grade of glioma with the highest expression level in WHO Grade IV (p < 0.0001)." (PMID 34123793, 2021). "In this study, the expression level was positively correlated with the clinical stage of glioma, which is consistent with previous findings on correlation of UBE2S expression level with tumor grades in other types of tumors." (PMID 34123793, 2021). "In this work, 2 large datasets of glioma patients from the TCGA and the CGGA databases, as well as the clinical data from 114 glioma patients were used to perform a comprehensive analysis on the role of UBE2S on glioma." (PMID 34123793, 2021). "Akt1 physically interacts with UBE2S and phosphorylates UBE2S at Thr152 in glioma cells, which is important for stabilization of UBE2S." (PMID 34123793, 2021). "Co-deletion of 1p19q, which is an indicator of optimistic outcome, was mainly observed in glioma with lower UBE2S expression level." (PMID 34123793, 2021). "UBE2S is highly expressed in several kinds of human cancers and is connected with the advancement of malignancy and worse prognosis in cancer of the ovary, prostate cancer, and glioma, among others." (PMID 41427004, 2025). "Out of 114 glioma specimens 58 (51%) showed significant UBE2S expression." (PMID 34123793, 2021). "Therefore, further studies should explore the mechanisms by which UBE2S promotes the apoptosis phenotype of glioma." (PMID 34123793, 2021). "Knockdown of UBE2S increases sensitivity of glioma cells to IR." (PMID 34123793, 2021). "In addition, UBE2S affected the degree of malignancy of glioma and the development of chemo-radiotherapy resistance." (PMID 34123793, 2021). "Analysis showed that UBE2S expression was positively associated with PTEN-mutation and EGFR amplification and negatively associated to IDH1-mutation and co-deletion of 1p19q in whole grade glioma." (PMID 34123793, 2021). "Furthermore, UBE2S exerted an impact on the pathogenesis of malignancy and radiotherapy resistance in gliomas and was identified as a significant prognostic factor for unfavorable survival outcomes in patients with low-grade gliomas." (PMID 38312603, 2024). "Therefore, UBE2S is a vital biomarker for predicting prognosis of glioma." (PMID 34123793, 2021). "Therefore, PTEN-Akt1 pathways may positively regulate UBE2S function in glioma tissue by enhancing its stability." (PMID 34123793, 2021). "The ubiquitin conjugating enzyme E2S (UBE2S) is commonly overexpressed in grade III and IV gliomas, being phosphorylated by AKT, which prevents its proteasomal degradation." (PMID 33665742, 2021). "UBE2S expression has been reported in various human cancers, however its role in glioma is not known." (PMID 34123793, 2021). "We found that UBE2S expression level was higher in grades III-IV glioma tumors (malignant glioma) compared with non-glioma brain tissue specimens or in grade II glioma tumors." (PMID 34123793, 2021). "However, its expression in glioma tissues and the potential correlation between UBE2S and clinical outcome in patients with glioma have not been explored." (PMID 34123793, 2021).
ovarian carcinoma (11 papers, 2021 to 2025). A malignant neoplasm originating from the surface ovarian epithelium. "Research has demonstrated that UBE2S is significantly upregulated in ovarian cancer and is linked to unfavorable outcomes." (PMID 38312603, 2024). "Considering that UBE2S was involved in the activation of Wnt/β-catenin signaling pathway and the Olaparib resistance in ovarian cancer, we examined the underlying relationship between them." (PMID 34535173, 2021). "The potential oncogenic role of UBE2S is significantly linked to unfavorable prognosis in ovarian cancer patients, and is responsible for the promotion of ovarian cancer development through the regulation of apoptosis and cell cycle via PI3K/AKT/mTOR signaling." (PMID 38312603, 2024). "Knocking down of UBE2S can inhibit the proliferation and migration of cisplatin-resistant ovarian cancer cells, providing new insights for the evaluation and treatment of high-risk ovarian cancer patients with cisplatin resistance." (PMID 39048965, 2024). "For instance, the ubiquitin-conjugating enzyme E2S (UBE2S) promotes PARPi resistance in ovarian cancer by activating Wnt/β-catenin signaling." (PMID 40191206, 2025). "In cancer of the ovaries, UBE2S increased the growth and Olaparib resistance of tumors in its enzymatic activity‐dependent technique." (PMID 41427004, 2025). "One study found that UBE2S is highly expressed in epithelial ovarian cancer and induces cisplatin resistance by activating the PI3K/AKT/mTOR signaling pathway and inhibiting autophagy." (PMID 39048965, 2024). "In an enzymatic activity-dependent manner, the Wnt/β-catenin signaling pathway is activated and upregulated by UBE2S in ovarian cancer, thereby augmenting proliferation and conferring resistance to olaparib." (PMID 38312603, 2024). "In summary, UBE2S represents a potential molecular mechanism for the progression and metastasis of ovarian cancer, promoting both ovarian cancer advancement and olaparib resistance via Wnt/β-catenin signaling." (PMID 38312603, 2024). "In vivo experiments demonstrated that UBE2S promoted the growth of cisplatin-resistant ovarian cancer transplant tumors in the nude mouse." (PMID 38115063, 2023). "The results of RT-qPCR and Western blotting indicated that UBE2S was significantly overexpressed in ovarian cancer cell lines compared with normal cell lines (P < 0.05)." (PMID 35658829, 2022). "UBE2S can promote the progression of many types of cancer, such as ovarian cancer, non-small cell lung cancer, colorectal cancer and prostate cancer." (PMID 36250027, 2022). "The quantification results showed that the overexpression of UBE2S significantly decreased the cell apoptosis and thus increased the Olaparib resistance in ovarian cancer." (PMID 34535173, 2021). "This study revealed for the first time that overexpression, biological significance, and functional mode of UBE2S in ovarian cancer." (PMID 34535173, 2021). "The high expression of UBE2S in ovarian cancer was related with lymph node metastasis and platinum resistance, but not with age, FIGO staging, CA125 level, and peritoneal metastasis." (PMID 34535173, 2021). "The transwell assay was used to analyze the effects of UBE2S on the migration and invasion of ovarian cancer cells." (PMID 34535173, 2021). "In the present study, we showed that overexpression of UBE2S promotes the proliferation and metastasis of ovarian cancer cells, while knockdown of UBE2S resulted in totally opposite phenotypes." (PMID 34535173, 2021). "All these findings confirmed that UBE2S confers ovarian cancer cells to Olaparib resistance through Wnt/β-catenin signaling pathway." (PMID 34535173, 2021). "UBE2S promoted ovarian cancer proliferation and drived the migration and invasion of ovarian cancer cells." (PMID 34535173, 2021). "UBE2S activates the Wnt/β-catenin signaling pathway in ovarian cancer to inhibit apoptosis, conferring Olaparib resistance in ovarian cancer cells." (PMID 34535173, 2021).
ovarian carcinoma (continued). "We also identified the overall UBE2S expression in ovarian cancer patients using microarray data from Kaplan-Meier Plotter, which showed a shorter overall survival time (HR = 1.24, p = 0.0069) in patients with high UBE2S expression." (PMID 34535173, 2021). "Our results indicated that UBE2S had the potential to be a novel biomarker for the development and drug resistance in ovarian cancer." (PMID 34535173, 2021). "UBE2S activated the Wnt/β-catenin signaling pathway in ovarian cancer resulting in Olaparib resistance in vitro and in vivo." (PMID 34535173, 2021). "The results from TCGA datasets also showed that the expression of UBE2S was relatively high in ovarian cancer tissues compared with control tissues." (PMID 34535173, 2021). "Notably, in ovarian cancer, UBE2S triggers Wnt/β-catenin signaling, leading to resistance to olaparib in vitro and in vivo." (PMID 38312603, 2024). "The inhibition of PI3K/AKT/mTOR pathway by UBE2S could induce apoptosis and impede the cell cycle, thereby restraining the invasion and proliferation of ovarian cancer cells and correlating with poorer survival prognosis." (PMID 38312603, 2024). "Cell invasion, migration and proliferation are promoted by UBE2S in ovarian cancer." (PMID 38312603, 2024). "Univariate and multivariate analysis identified UBE2S as an independent factor for ovarian cancer." (PMID 35658829, 2022). "Taking these results of this study together, it was reasonable to speculate that UBE2S may promote the malignant progression of ovarian cancer cells by promoting the PI3K/AKT/mTOR signaling pathway and thereby promoting cell cycle and inhibiting apoptosis." (PMID 35658829, 2022). "After confirming the abnormal overexpression (the genetic level) and prognostic significance (the clinical level) of UBE2S in ovarian cancer, the influence of UBE2S on the biological behavior of cells (the level between the genetic level and the clinical level) was tried to explored." (PMID 35658829, 2022). "However, the function of UBE2S in the development and Olaparib resistance of ovarian cancer are unclear." (PMID 34535173, 2021). "Likewise, the clonogenic assay showed that overexpression of UBE2S significantly decreased the Olaparib sensitivity in ovarian cancer cells, in which the cell growth was obviously enhanced." (PMID 34535173, 2021). "However, the biological function and prognostic significance of UBE2S in ovarian cancer are not fully understood." (PMID 34535173, 2021). "Furthermore, UBE2S enhanced the proliferation and Olaparib resistance of ovarian cancer in its enzymatic activity dependent manner." (PMID 34535173, 2021). "In addition, UBE2S promotes ovarian cancer cell proliferation, metastasis, and chemotherapeutic resistance." (PMID 34535173, 2021). "Our study indicates that UBE2S may be a therapeutic target in ovarian cancer, suggesting future directions to enhance the survival of ovarian cancer." (PMID 34535173, 2021). "Furthermore, consistent trends between UBE2S and RNA modification related genes (including m1A, m5C, and m6A) were also observed in numerous tumors such as esophageal carcinoma, adenoid cystic carcinoma, and ovarian cancer." (PMID 41427004, 2025). "Knockdown of UBE2S could block the cell cycle and promote apoptosis by inhibiting the PI3K/AKT/mTOR pathway and ultimately inhibit the proliferation, migration and prognosis of ovarian cancer, which suggested that UBE2S might be used for molecular therapy and prognostic evaluation of ovarian cancer." (PMID 35658829, 2022). "Therefore, the results of apoptosis-related flow cytometry and western blotting together suggested that the knockdown of UBE2S may promote the apoptosis of ovarian cancer cells by regulating the expression of apoptosis-specific proteins." (PMID 35658829, 2022).